BCAN (brevican)
Diseases named in the same sentence as BCAN in open-access papers (continued):
Sharing a sentence is not in itself a finding about the gene and the disease.
epilepsy (3 papers, 2022 to 2025). A brain disorder characterized by episodes of abnormally increased neuronal discharge resulting in transient episodes of sensory or motor neurological dysfunction, or psychic dysfunction. "Epilepsies with a genetic basis can manifest early in life, and both BCAN and NCAN are believed to play crucial roles in terminal differentiation during development, as well as in the adult nervous system during postnatal development." (PMID 36980356, 2023). "While one study found via immunoblot of post mortem human epilepsy hippocampus samples a reduction of total brevican immunoreactivity a more recent study reported upregulated brevican levels in human post mortem frontal cortex samples from epilepsy patients as compared to controls." (PMID 35480959, 2022).
ischemia (3 papers, 2017 to 2023). A hypoperfusion of the BLOOD through an organ or tissue caused by a PATHOLOGIC CONSTRICTION or obstruction of its BLOOD VESSELS, or an absence of BLOOD CIRCULATION. "On the other hand, ischemia evoked a significant downregulation of genes associated with the protective functions of ECM molecules (e.g., brevican, Hapln4); this downregulation was also more prominent in the aged mice." (PMID 38107409, 2023).
melanoma (3 papers, 2022 to 2025). A malignant, usually aggressive tumor composed of atypical, neoplastic melanocytes. "For example, BCAN is significantly differentially expressed in IFN-treated melanoma, and promoter mutations of TERT in melanoma and COL1A1 promote melanoma invasion, among others." (PMID 40350499, 2025). "From this perspective, it is of note that the IFN therapy and the ICI therapy predictive genes of our IFN resistance DEGs overlapped by three genes, WFDC1, SOX4, and BCAN, strongly suggesting a connection between the two pheno-/geno-types of melanoma: IFN and ICI resistance." (PMID 35269844, 2022). "BCAN (brevican) is a chondroitin sulphate proteoglycan of the ECM, with no data on its role in melanoma." (PMID 35269844, 2022). "Our in silico analysis of IFN-treated melanoma tissues of TCGA revealed the differential expression of five members of our 79 IFN-res DEGs in IFN-treated melanoma tissues: IRG SOX4 and non-IRGs WFDC1, BCAN, RPE65, and MAPT." (PMID 35269844, 2022).
vascular dementia (3 papers, 2021 to 2026). A degenerative vascular disorder affecting the brain. "were able to discriminate between AD and vascular dementia patients by measuring the BCAN concentration in CSF." (PMID 36788617, 2023). "We recently reported that CSF brevican and neurocan peptide concentrations were decreased in vascular dementia compared with healthy controls, and thus it was of interest to explore their levels in iNPH patients who showed vascular-based pathology." (PMID 33985551, 2021).
astrocytoma (2 papers, 2012 to 2025). "Next, we evaluated BCAN, GFAP, and VEGF-A in Patient 46, who had stable IDH-mutant grade 4 astrocytoma post-resection and chemoradiation." (PMID 39786485, 2025).
glioneuronal tumor (2 papers, 2020 to 2022). "An adult patient with a BCAN:NTRK1 fused glioneuronal tumor developed disease progression after eleven months of entrectinib." (PMID 33353026, 2020). "Alvarez-Breckenridge described a case of low-grade glioneuronal tumor with BCAN::NTRK1 fusion." (PMID 36531047, 2022).
lung adenocarcinoma (2 papers, 2020 to 2024). A carcinoma that arises from the lung and is characterized by the presence of malignant glandular epithelial cells. "A recent study reported that BCAN, as a component in the basement membrane, possesses predictive potential for prognosis in the lung adenocarcinoma." (PMID 38791985, 2024). "However, higher BCAN levels might also be related to worse prognosis in lung adenocarcinoma (LUAD)." (PMID 38791985, 2024).
Anxiety (1 paper, 2022). Intense feelings of nervousness, tension, or panic often arise in response to interpersonal stresses. "Tenascin-R knockout mice display an impairment of motor coordination and increased anxiety levels, while brevican knockout mice did not exhibit deficits in learning and memory." (PMID 35714111, 2022).
cognitive decline (1 paper, 2020). "It is not yet known what role CSPGs and the PNN may play in age-related cognitive decline; however, our data suggest that NCAN and BCAN are associated with brain volume and may potentially play a neuroprotective role for general fluid cognitive ability in early adulthood." (PMID 32041957, 2020).
delirium (1 paper, 2026). A disorder characterized by confusion; inattentiveness; disorientation; illusions; hallucinations; agitation; and in some instances autonomic nervous system overactivity. "Other notable proteins robustly associated with delirium in our proteomic analysis are BCAN, SELENOP, AREG and MSLN." (PMID 41286463, 2026). "BCAN, a protein with a role in brain extracellular matrix formation, has been observed to be downregulated in brains of post-infection delirium and in patients with AD73." (PMID 41286463, 2026).
glaucoma (1 paper, 2021). Increased pressure in the eyeball due to obstruction of the outflow of aqueous humor. "Remarkably, we found comparable protein and mRNA levels of these proteoglycans, which indicates a damage-independent expression of aggrecan and brevican in our glaucoma model." (PMID 33668263, 2021).
injury (1 paper, 2019). Damage inflicted on the body as the direct or indirect result of an external force, with or without disruption of structural continuity. "OPG, RGMB, and ROBO2 have been implicated in CNS development, axonal growth, and recovery after nerve injury, whereas upregulation of brevican has been observed in the CNS during the consolidation of long-term memories." (PMID 31694701, 2019).
Intraventricular hemorrhage (1 paper, 2023). Bleeding into the ventricles of the brain. "Similarly, there is an upregulation of aggrecan, brevican, neurocan and versican in rabbit pups after intraventricular hemorrhage." (PMID 38025264, 2023).
multiple sclerosis (1 paper, 2022). A progressive autoimmune disorder affecting the central nervous system resulting in demyelination. "Both tenascins interact with various chondroitin sulfate proteoglycans (CSPGs) of the lectican family such as versican and brevican and thus partake in the inhibitory environment that restricts regeneration of myelin, in particular in multiple sclerosis lesions." (PMID 35681468, 2022).
Neonatal sepsis (1 paper, 2025). Systemic inflammatory response to infection in newborn babies. "The additional decreases in structural ECM proteins such as brevican, nidogen-1 and −2, and fibronectin suggest that neuroinflammatory damage in neonatal sepsis may involve degradation of the ECM, potentially contributing to long-term neurological complications." (PMID 40927580, 2025).
oligodendroglioma (1 paper, 2019). A well-differentiated (WHO grade II), diffusely infiltrating neuroglial tumor, typically located in the cerebral hemispheres. "A pilot study on 5 matched 1p/19 co-deleted and 1p/19q non-deleted oligodendrogliomas revealed Brevican core protein (BCAN) and Serotransferrin (TRFE) as possible biomarkers for the co-deleted 1p/19q phenotype." (PMID 31357616, 2019).
prostate tumours (1 paper, 2013). "In this study, expression of cell surface and stromal proteoglycans (glypican-1, perlecan, syndecan-1, aggrecan, versican, NG2, brevican, decorin, and lumican) in normal tissue and prostate tumours was determined by RT-PCR analysis and immunostaining with core protein- and GAG-specific antibodies." (PMID 23691363, 2013).
steatosis (1 paper, 2024). Increased lipid within the cytoplasm of cells. "In this group, CD63 and CD38 positively correlated with steatosis grade, while NCAN and BCAN positively correlated with bioimpedance values." (PMID 39407757, 2024).
ZIKV infection (1 paper, 2023). "Interestingly, ZIKV infection did not alter mRNA expression or total protein levels of aggrecan and brevican, however, it led to an increase in the cleaved forms of aggrecan and brevican proteins." (PMID 37496706, 2023).
tumor (31 papers, 2012 to 2026). "ex., typical tumor drivers BCAN, APOE, and EGFR or genes associated to neuronal function like EGR1, FOS, and MARCKS)." (PMID 40188875, 2026). "BCAN remodels the extracellular matrix and activates pro-invasive pathways, facilitating tumor invasion." (PMID 41584609, 2025). "Using three spatially-enriched marker genes for each tumor subregion (CT: BCAN, CSPG5, TOP2A; Pseudo: HILPDA, IGFBP5, LGALS3; and MVP: MGP, LUM, THBS1) we identified distinct sub-populations of malignant cells from the scRNA-seq data." (PMID 41366031, 2025). "In our study, the expression of BCAN in the tumor and high CRRS groups was significantly higher than in normal tissues and the low CRRS group." (PMID 36717900, 2023). "An ECM glycoprotein expressed exclusively in the central nervous system (CNS) called brevican (Bcan) is upregulated in GBM, and is linked to increased tumor invasion and aggressiveness." (PMID 35565337, 2022). "Despite declining BCAN, GFAP, and VEGF-A, T1-gadolinium–positive tumor volume increased until POD552, likely indicating pseudoprogression." (PMID 39786485, 2025). "The epitopes are derived from four TAAs that are either over-expressed (BCAN, BIRC5, PTPRZ1) or where the epitope is over-presented (NLGNX4) in a large proportion of GBM tumours compared with most healthy tissues." (PMID 41051649, 2025). "Three of the TAAs (BCAN, PTPRZ1, BIRC5) are highly over-expressed in GBM tumours compared with healthy tissue (except testis)." (PMID 41051649, 2025). "TNXB and brevican (BCAN) are usually heavily glycosylated, remodel the ECM and promote motility, creating a scaffold that facilitates tumor growth, migration, and invasion." (PMID 41440381, 2025). "Top differentially suppressed genes as the tumor transformed included SMOC1, BCAN, NES, AIF1L, ENC1, and IGF2 (p < 0.01)." (PMID 39256867, 2024). "Targeted NGS was performed on RNA extracted from the tumor and uncovered a fusion (confirmed by FISH), involving BCAN exon 13 fused to NTRK exon 11, including an intact and in-frame tyrosine kinase domain of TrkA." (PMID 29872694, 2017). "Notably, BCAN, VCAN, and JAM2 were predominantly expressed by tumor cells, while ITGB1 was ubiquitously expressed across all clusters." (PMID 39554845, 2024). "The concordant changes in protein expression results with the values detected at the gene expression can be observed in all the evaluated parameters of integrin αV, brevican, CSPG-5, versican, integrin β-5, and CD44 and only in tumor staining in the case of MDM2, MMP2, and FLT-4." (PMID 39595920, 2024).
cancer (9 papers, 2012 to 2025). A tumor composed of atypical neoplastic, often pleomorphic cells that invade other tissues. "An increase in BCAN in GBM has been linked to increased invasiveness, and sialylation in cancer is related to adhesion and invasion mechanisms increasing metastatic potential of cancer cells." (PMID 35202840, 2022). "Several have been proposed for the detection of PDAC or other cancers in blood, including BCAN, IKZF1, TBX15, BNC1 and SHOX2." (PMID 36434648, 2022). "Cells exhibiting high expression of BCAN, GFAP, and EGFR were categorized as cancer cells, while endothelial cells displayed elevated levels of FLT1, CLDN5, and ABCG2." (PMID 41041071, 2025). "Some other proteoglycans such as aggrecan, neurocan, brevican, biglycan, lumican, glypicans, fibromodulin, agrin, collagen XVIII, NG2, and serglycin are also involved in cancer progression, but their expression and functional role have not yet been investigated in prostate cancer." (PMID 23691363, 2013). "Therefore, the observed downregulation of BCAN, NCAN, and VCAN in Etoposide resistant RB cells contrasts with the expression pattern in adult cancer but might represent the expression pattern in childhood tumors." (PMID 32560557, 2020).
infection (3 papers, 2016 to 2026). The state of being infected such as from the introduction of a foreign agent such as serum, vaccine, antigenic substance or organism. "During acute infection and while the proinflammatory cytokines were elevated, the staining intensity of WFA remained low and the cleaved forms of aggrecan and brevican were elevated suggesting increased degradation during infection and inflammation." (PMID 37496706, 2023). "In this study, using a model of ZIKV neonatal infection, we showed that the development of PNNs is disrupted by infection resulting in a marked reduction in PNN density that is associated with an increase in cleaved forms of aggrecan and brevican." (PMID 37496706, 2023). "In TMEV infection, immunolabeling of brevican in murine spinal cord did not change with respect to distribution or intensity." (PMID 27441688, 2016).
heart disease (1 paper, 2019). "A number of studies have proposed the contribution of versican in ECM remodeling and heart disease, but the role of aggrecan (a cartilage proteoglycan with potential role in vascular stiffness), neurocan (specific to neuronal tissue), and brevican in heart disease remains unexplored." (PMID 31547598, 2019).
BCAN also shares sentences with these, for which no sentence is quoted: malignant glioma (2 papers); anaplastic astrocytoma (1); bipolar depression (1); brain glioma (1); brain injuries (1); cardiovascular disease (1); dilated cardiomyopathy (1); Focal cortical dysplasia (1); ischemic cardiomyopathy (1); laryngeal carcinoma (1); neurodegenerative disease (1); neurodevelopmental disorder (1); neurological disorders (1); Parkinson disease (1); prostate carcinoma (1); schizophrenia (1).